BRCA1 (BRCA1 DNA repair associated)
Diseases named in the same sentence as BRCA1 in open-access papers (continued):
Sharing a sentence is not in itself a finding about the gene and the disease.
tumor (continued). "Notably, one BRCA1/2 wild-type TNBC tumor that had low Trop-2 expression and was proficient in HRR, namely MDA-MB-231 (~30,000 surface Trop-2 molecules per cell), was not responsive to this combination." (PMID 33196706, 2020). "Whether translational control could be a novel function of BRCA1 contributing to its tumor suppressor capabilities remains however to be assessed." (PMID 32290274, 2020). "Patients with BRCA1 hypermethylated tumors were significantly younger at diagnosis compared to the patients negative for both tumor methylation and BRCA1/2 loss of function variants (median age 36 versus 50 years, t-test, p = 8e−5)." (PMID 32719340, 2020). "These proteins are respectively implicated in mRNA splicing and apoptosis, DNA replication, and cell cycle regulation, transcription repression of pro-proliferative signaling, all biological functions known to contribute to the tumor suppressive activity of BRCA1." (PMID 32290274, 2020). "BRCA2 mutation was more frequently detected than BRCA1 mutation regardless of the location of the tumor in males and accounted for 56.7–100.0% of the cases." (PMID 33054725, 2020). "Stathmin alone predicted BRCA1 mutation status among ER negative tumours in a subgroup (n = 25) of patients under 40 years (p = 0.032)." (PMID 32076022, 2020). "Intriguingly, the BRCA1-null tumor cells could be segregated further into cells with basal (Cluster 4) and mesenchymal (Cluster 5) features, respectively." (PMID 32840210, 2020). "Moreover, we show that in terms of mutational, epigenetic, transcriptional, and immune infiltration profiles, BRCA1 hypermethylation confers a tumor phenotype practically identical to that of BRCA1-null cases." (PMID 32719340, 2020). "However, the apoptotic rate of T47D cells significantly increased after the activation of PI3K, which is possibly due to the tumor suppressor function of phosphorylated BRCA1, leading to an increased apoptosis rate of cells." (PMID 33817238, 2020). "The recent POLO trial showed that in patients with chemotherapy responsive BRCA1/2-mutated tumors, 22.1% of patients treated with Olaparib did not have any tumor progression after two years." (PMID 33015058, 2020). "BRCA1 translocates to DNA damage sites and coordinates both DNA damage repair and DNA damage signaling, which are essential for maintaining genomic stability and suppressing tumor formation." (PMID 32257107, 2020). "The present study also confirmed that BRCA1/2-mutated tumors showed a higher incidence of contralateral breast recurrence compared to non-mutated tumor (non-mutated versus BRCA1/2-mutated tumors: 4.9% vs. 26.0%, p < 0.001)." (PMID 33019612, 2020). "Five of the six long-term responders alive at a median of 4.5 years lacked germline BRCA1/2 mutations, and two of them had increased tumor HRD-LOH/HRD-LST scores." (PMID 32605126, 2020). "This is particularly true for patients with BRCA1/2wt tumours." (PMID 32833070, 2020). "All the BRCA1-associated tumours were ER negative, compared with 33% of the non-BRCA1-associated tumours." (PMID 33081408, 2020). "According to BRCA mutation status, BRCA1/2-mutated tumors showed a higher incidence of contralateral breast recurrence compared to non-mutated tumor (non-mutated vs. BRCA1/2-mutated tumors: 4.9% vs. 26.0%, p < 0.001)." (PMID 33019612, 2020).
tumor (continued). "To confirm this, we investigated whether inhibition of inflammasome activity could reactivate CD8+ T cells and alleviate Brca1 mutant tumor progression." (PMID 32195105, 2020). "Surprisingly, despite biological plausibility for the existence of an association between BRCA1/2 mutations and MF/MC tumours, at the time of writing, there were no studies investigating this." (PMID 32022473, 2020). "Furthermore, two studies highlighted that sporadic tumours with hypermethylated BRCA1 promoters exhibit expression profiles similar to BRCA1 pathogenic variants." (PMID 33081408, 2020). "However, the methylation profile varies across individual CpG nucleotides, and a recent study found LOH for BRCA1 as well as BRCA2 to occur in concert with promoter methylation of the same gene in different subclones of the same tumor." (PMID 31225507, 2019). "BRCA-1 (breast cancer type 1) is another tumor suppressor gene." (PMID 30781847, 2019). "Another critical interactor of TOP2A is the tumor suppressor and DNA repair gene BRCA1." (PMID 31083655, 2019). "Furthermore, western blots revealed that BRCA1 expression in tumor samples was less than that of OVCAR8 cells grown in culture." (PMID 31117198, 2019). "Interestingly, two of four BRCA1 mutated cases presented a response to platinum retreatment while in two patients with XRCC2 mutation, one presented a stable disease and the other tumor progression." (PMID 31060523, 2019). "Consistently, we found a significant reduction in tumor growth and increased levels of BRCA1 and RAD17 in xenografted tumors arising from the HNSCC CAL27 cell line, orthotopically and intrascapularly injected in immunocompromised mice and subsequently treated with miR-205-5p synthetic inhibitors." (PMID 31514456, 2019). "Differences in patient and tumor characteristics of BRCA1/2 carriers who were already identified as part of clinical BRCA1/2 testing routines and additional BRCA1/2 carriers found by sequencing the entire study population were compared using logistic regression models." (PMID 30175445, 2019). "Furthermore, there is growing evidence that loss of breast cancer type 1 susceptibility protein (BRCA1) is associated with EMT and tumor initiation." (PMID 31213009, 2019). "The mixed phenotype of Palb2-KPC tumors could be due to the role of PALB2, as a linker protein between BRCA1 and BRCA2, in BRCA1/2 mediated tumor suppression." (PMID 31877165, 2019). "Therefore reliable diagnostic tests for the detection of BRCA1/2 mutations and variants in other genes involved in DDR in tumor tissues are crucial for treatment decision making." (PMID 31029168, 2019). "Observations that the BRCT domains are frequently targeted by many clinically important mutations and that most of these mutations disrupt the binding surface of the BRCT domains to phosphorylated peptides indicate that the BRCT domains are integral for the tumor suppressor function of BRCA1." (PMID 30006610, 2019). "In light of the role of BRCA1 in the regulation of both coding and non-coding RNAs34,45, we hypothesized that the status of BRCA1 would affect tumor cell response to histone deacetylases." (PMID 31273285, 2019). "To determine whether the decreased expression of BRCA1 was due to persistent methylation, we evaluated the degree of methylation at the BRCA1 promoter region in all tumor samples." (PMID 31117198, 2019). "BRCA1 is a tumor suppressor that plays a role in the repair of double-stranded DNA breaks." (PMID 31213009, 2019).
tumor (continued). "Since BRCA1/BRCA2 mutations have not been found in RMS tumours, the presence of genetic/epigenetic alterations in other DNA repair machinery components or related factors cannot be excluded." (PMID 30357520, 2019). "While maintenance of genomic integrity is essential to BRCA1 tumor suppressor function, it alone does not easily explain the cell lineage-specific deficiency that occurs at early stages of tumorigenesis in BRCA1 mutation carriers." (PMID 30995943, 2019). "BRCAnesswas described as a phenomenon in which HR deficiency occurs in a tumor not dueto a BRCA1 or BRCA2 germline mutation, but bymutations in other genes involved in HR." (PMID 31067289, 2019). "Disrupting either the DNA annealing factor RAD52 or the A-family DNA polymerase POLQ can cause synthetic lethality with defects in BRCA1 and BRCA2, which are tumor suppressors important for homology-directed repair of DNA double-strand breaks (DSBs), and protection of stalled replication forks." (PMID 31381562, 2019). "The frequency of BRCA1/2 mutations was higher in patients with the tumor test requested at least 6 months after diagnosis without disease-relapse." (PMID 31653094, 2019). "Prediction of BRCA1/BRCA2 carrier status, and hence selection of women for mutation screening, may be substantially improved by combining tumor pathology with family history." (PMID 31244284, 2019). "We also evaluated the tumor histology and immunohistochemical characteristics of the tumors and whether they were influenced by AAO among BRCA1 mutation carriers." (PMID 31395037, 2019). "As a tumor suppressor, FOXA1 overexpression might block metastatic progression by influencing the expression of p27 (BRCA1 associated cell cycle inhibitor) and promoting E-Cadherin expression." (PMID 30819139, 2019). "Although the mechanisms remain to be examined, these data suggest that the BRCA1 status may determine tumor response to HDAC inhibitors." (PMID 31273285, 2019). "Indeed, the BRCT domain of BRCA1 has been shown to be important for cell cycle checkpoint, HR, and tumor suppression." (PMID 30006610, 2019). "The evidence that PALB2 is critical for HR and functions as a breast and pancreatic susceptibility gene suggest that the role of the adaptor protein, PALB2, may be critical for BRCA1/2- mediated tumor suppression by physically linking BRCA1 to BRCA2." (PMID 31877165, 2019). "Importantly, VHIO179, a tumour carrying BRCA1 germline truncation, is resistant to treatment with PARP inhibitors due to a MAD2L2 (REV7) inactivating mutation." (PMID 31273933, 2019). "Tumor suppressor genes such as BRCA1 may also affect the metabolic phenotype of stromal cells in the tumor microenvironment." (PMID 30691108, 2019). "The interaction between BRCA1 and HDACs suggests that the BRCA1 status may affect tumor cell response to HDAC inhibitors." (PMID 31273285, 2019). "Additionally, this approach detected heterozygous deletions of the entire BRCA1 gene as the second hit in four of the tumor samples." (PMID 31029168, 2019). "In all laboratories, a pathologist reviewed the tumor specimen before molecular BRCA1/2 assay." (PMID 31600986, 2019). "BRCA1 is methylated in up to 30% of these tumours and OPCML is methylated in over 80% of OT." (PMID 31450846, 2019).
tumor (continued). "Cisplatin treatment of one BRCA1-mutated PDX model to non-palpable levels had a surprisingly minor impact on clonal diversity in the relapsed tumor yet purged 50% of distal clones." (PMID 30770823, 2019). "PARP inhibitors may benefit patients whose tumours are dysfunctional in DNA repair mechanisms unrelated to BRCA1/2." (PMID 30353044, 2018). "These deregulated miRNAs are not specific to Brac1 knockout mammary glands or BRCA1-associated tumours as they were also deregulated in non-familial tumours." (PMID 30323900, 2018). "BRCA1 is a tumor suppressor gene located on chromosome 17q21." (PMID 29492227, 2018). "Whether this is unique to either PCa in specifically or BRCA1/2 wild‐type tumor cells in general is an area of active interest." (PMID 30467127, 2018). "Eight of the 12 cases (#15–21) had homozygous BRCA1 methylation in the pre-treatment tumor biopsy, six of these (#16–21) were high confidence calls based on neoplastic cellularity of >20% (these six cases are hereafter referred to as the homozygous BRCA1 methylation (high confidence) subgroup)." (PMID 30266954, 2018). "However, upregulation TGF-β1 decreased the level of BRCA1 and Smad3 phosphorylation in tumor tissues." (PMID 30594239, 2018). "Consistent with the idea of the activation of a regulatory cascade is a report showing that miR-335 may exert its tumor-controlling effects via upregulation of BRCA1 mRNA28." (PMID 30514916, 2018). "Indeed, our data strongly suggest that methylation zygosity should be assessed in contemporaneous tumor samples before any firm conclusions are drawn regarding the impact of BRCA1 methylation on therapeutic efficacy." (PMID 30266954, 2018). "However, the difference in BRCA1 expression levels, based on the tumor subtypes, has rarely been reported." (PMID 28646826, 2018). "Therefore, tumor formation induced by Sei-1 is likely related to the low expression of BRCA1 and Abraxas." (PMID 29497033, 2018). "BRCA1 is a multifunctional tumor suppressor involved in several essential cellular processes." (PMID 29757984, 2018). "Like BRCA2- and CHEK2-associated tumours, ATM-associated tumours are mostly luminal tumours but they do not show a particular histological subtype as observed in BRCA1- (medullary), BRCA2- (lobular), CDH1- (lobular), and PTEN-associated tumours (apocrine)." (PMID 29665859, 2018). "During tumor initiation, its loss not only triggers tumor-survival signals including PI3K/Akt and MAPK, but also leads to the inactivation of tumor suppressor genes such as BRCA1 and PTEN." (PMID 30333750, 2018). "Therefore, a conditional Lyn knockdown system in which mouse Brca1 tumor cells expressed shRNA against Lyn under the control of doxycycline was established." (PMID 30590041, 2018). "Deleterious mutations of BRCA1 often cause disrupted BARD1/BRCA1 interaction, suggesting that the formation of a stable BARD1/BRCA1 complex may be an essential aspect of BRCA1 tumor suppression." (PMID 29686231, 2018). "BRCAness is a phenocopy of BRCA1/2 mutations, in fact, HR mechanisms result defective although tumor cells do not carry mutations in BRCA1/2 genes." (PMID 30234015, 2018). "Our results show that RAD51 foci in PDX tumor samples correlated with PARPi response, while BRCA1 promoter hypermethylation, BRCA1 expression, BRCA1 foci, or HRR gene mutations did not fully correlate with PARPi response." (PMID 30377213, 2018). "Further functional studies of putative BRCA1 target genes may help to fully understand the roles of this multifunctional tumor suppressor." (PMID 29757984, 2018). "The proliferation of Brca1-mutant tumor cells decreased as the amount of cyclin B1 increased." (PMID 30327455, 2018). "Mutations in BRCA1 and BRCA2 (hereafter referred to as BRCA1/2), the most important genetic susceptibility markers, account for up to 15% and 30% of the familial recurrence risk (FRR) of overall and high-risk breast cancers." (PMID 30323354, 2018).
tumor (continued). "The BRCA1/2 genes are, therefore, considered tumour suppressor genes and are likely to require biallelic LOF for tumorigenesis to occur; in keeping with Knudson’s double-hit hypothesis." (PMID 29464354, 2018). "The analysis of genomic DNA showed that loss of Brca1 was exclusively detected in the tumor tissues from mutant mice but not in the normal lacrimal gland of wild-type mice." (PMID 30652068, 2018). "We observed that eight of the nine (miR-16-5p not in dataset) miRNAs deregulated during development and BRCA1 mutated tumours were also differentially expressed in these subsets of the human breast." (PMID 30323900, 2018). "AR + /FOXA1 + tumours (42.4%) were more frequently: found in older patients, lobular, of lower nuclear grade, with more frequently PIK3CA mutations; exhibited less frequently BRCA1 promoter methylation, defects of PTEN and PD-L1 expression than others." (PMID 29880907, 2018). "We next assessed whether PARP1 mutations could cause PARPi resistance in a clinically relevant setting, such as in BRCA1 mutant tumour cells." (PMID 29748565, 2018). "Similar results were found in BRCA1- and BRCA2-associated tumours." (PMID 29665859, 2018). "In ID8hPON2 cells, the expression profile of many genes known to regulate tumor growth including BRCA1, cyclin and cyclin-dependent kinase 20, PTK2, Hypoxia-upregulated protein 1, p21-activated kinase 3, IL-18, IL-33, IGF-1, IGFBP2 and RNA-binding protein 9, were identified." (PMID 29531225, 2018). "We can speculate that the miRNAs involved in the regulation of DNA repair genes could represent a novel strategy to mimic the BRCAness phenotype, making tumor cells BRCA1/2 wild type more responsive to PARP inhibitors." (PMID 30234015, 2018). "In summary, these in vitro results confirmed that estrogen activates EMT in a subset of Brca1-deficient tumor cells with epithelial features, which is independent of ER." (PMID 29996906, 2018). "Interestingly, there is a clinical trial recruiting patients with advanced BC with BRCA1/2 promoter hypermethylation to analyze the response to olaparib monotherapy, which includes tumor sample collection for biomarker analysis (NCT03205761)." (PMID 30377213, 2018). "Next, we evaluated the effects of LYN knockdown on Brca1 tumor cell growth." (PMID 30590041, 2018). "We have demonstrated that compared to primary chemoresistant HGSOC, LT survival in HGSOC can be characterized by elevated mutation burden, biallelic inactivation of BRCA1 or BRCA2, and increased CD4+ and CD8+ lymphocytic infiltration in the tumor microenvironment." (PMID 30382883, 2018). "Together, these results indicate that estrogen promotes EMT in Brca1-deficient, but not in Brca1-proficient, tumor cells." (PMID 29996906, 2018). "Morphology of ATM-associated tumours was compared with that of 599 patients with no BRCA1 and BRCA2 mutations from a hospital-based series, as well as with data from The Cancer Genome Atlas." (PMID 29665859, 2018). "We found that estrogen activates EMT independent of ER in Brca1-deficient but not Brca1-proficient tumor cells." (PMID 29996906, 2018). "BRCA1 is a tumor suppressor that regulates DNA repair by homologous recombination." (PMID 29511213, 2018). "Recent work has suggested that PLD may enhance the immune response in BRCA1-deficient tumours, and this may contribute to the improved benefit from PLD seen in BRCA1/2-aberrant tumours." (PMID 29298688, 2018).